IL10 (interleukin 10)
Diseases named in the same sentence as IL10 in open-access papers (continued):
Sharing a sentence is not in itself a finding about the gene and the disease.
steatosis (continued). "In addition, evaluations of serum ALT levels, hepatic TG, and H&E staining of liver tissue revealed that liver damage and steatosis were obviously alleviated in IL-10−/− mice compared with WT controls." (PMID 29163491, 2017). "Thus, we assessed serum levels of neuron-specific enolase (NSE), transglutaminase 2 (TGM2), and glial fibrillary acidic protein (GFAP) as indirect markers of BBB dysfunction and examined their associations with steatosis severity, TNF-α and IL-10 in patients with morbid obesity." (PMID 42195075, 2026). "Moreover, after the treatment with the association, the increment in the expression of the genes related to cell survival, AKT1, MAPK8, PIK3CA (four times), and FAS (eight times), and to anti-inflammatory signaling, IL10 (four times), was observed in respect to the steatosis control." (PMID 36770927, 2023). "Several parameters distinguished patients with simple steatosis at the early MASLD stage from those with steatosis with inflammation – advanced MASLD, including Foxp3+ [% of CD4+CD25+]; IL-10 [MFI in CD4+ and CD4+CD25+ populations]." (PMID 40918132, 2025). "Specifically, the deletion of IL-10 results in IL-6/STAT3 mediated inflammatory response in the liver, decreasing steatosis." (PMID 41514930, 2025). "CD47 deficiency enhances NF-κB activation, elevates IL-1β, TNFα, IL-6, reduces IL-10, increases CCL2 and macrophage infiltration, leading to exacerbated steatosis, inflammation, and fibrosis." (PMID 40630093, 2025). "In IL-10(−/−) animals, further deletions of IL-6 or hepatic STAT3 increased the inflammatory response in the liver but reversed steatosis and hepatocellular damage." (PMID 38535313, 2024). "In this study, we focused on the role of IL-22, IL-9, IL-10 and IL-13 in CHC, particularly in the context of steatosis." (PMID 39200991, 2024). "Inflammatory biomarkers IL-1β, IL-6, IL-8, IL-10, and TNFα were all significantly elevated in the NAFLD/NASH patients, with respect to control participants and patients with simple steatosis." (PMID 36589452, 2022). "The results also revealed that both IL-6 and IL-10 concentration was reduced in the liver, accompanied by lower apoB protein expression and resulting TAG accumulation (steatosis)." (PMID 20920329, 2010). "On the other hand, in the absence of steatosis, we observed that levels of these same parameters reflecting damage and inflammation were similar in the BD+anti-IL-10+LT group and in the BD+LT group." (PMID 37593740, 2023). "Herein, we show new endogenous signaling pathways in LT from DBDs, namely, IL-6/IL-1β in non-steatotic liver grafts and IL-10/L-1β in steatotic ones; these different mechanisms that depend on the presence of steatosis had not been reported to date." (PMID 37593740, 2023). "Thus, depending on the presence or absence of steatosis, induction of BD downregulated different anti-inflammatory interleukins: IL-6 for non-steatotic and IL-10 for steatotic grafts." (PMID 37593740, 2023). "IL-10 may play a dual role in controlling liver injury via proinflammatory cytokine TNF-α inhibition and ethanol-induced steatosis, leading to potentiating alcoholic liver injury and ameliorating alcoholic liver injury, or via the inhibition of the hepatoprotective cytokine IL-6." (PMID 26508814, 2015). "Whereas other steatosis-promoting inflammatory cytokines, such as TNF-α and IFN-γ, are also increased in mice lacking IL-10, their effect is masked by IL-6/STAT3 anti-lipogenic properties." (PMID 41514930, 2025). "As the putative protective role for IL-10 was only based on in vitro findings, we believe that the reduced Il10 expression in liver of MKO mice upon HFD is unlikely to contribute to aggravated steatosis." (PMID 33273527, 2020). "While we also observed a tendency to lower Il10 expression in livers from MKO mice upon HFD feeding and a significant decrease upon CDAA diet feeding, we did not observe any exacerbation of steatosis or NASH." (PMID 33273527, 2020).
gingivitis (27 papers, 2018 to 2026). A disorder involving inflammation of the gums; may affect surrounding and supporting structures of the teeth. "In addition, part of SIgA may combine with T cells in the body, and as a result, cause secretion of cytokines, such as TGF-β, IL-4 and IL-10 to strengthen local immune function and further mobilize the body’s own immune response to gingivitis." (PMID 34234776, 2021). "Salivary cytokine profile differed according to oral condition: caries was associated with reduced IL-4, IL-10, and IFN-γ; gingivitis with elevated IL-1Ra and RANTES; and both conditions with increased IL-1β (p-value < 0.05)." (PMID 41505053, 2026). "In particular, according to the reported studies, genetic polymorphisms of VDR TaqI (rs731236), CD14 −260C/T, IL10-592-C, IL-1Ra, and TLR4-299-G were associated with higher risk of developing gingivitis." (PMID 41300760, 2025). "Eight of these studies investigated gingivitis in comparison with gingival health, and the genetic variants investigated mainly included SNPs of cytokine genes, such as IL1, IL6 and IL10, as well as an MMP gene." (PMID 40197750, 2025). "In contrast, DMN patients with gingivitis showed a trend in higher levels of IL-10, TNF-α, IgA and NF-κB while α-amylase was lower." (PMID 35788667, 2022). "Results of the present study revealed significantly higher levels of SIgA in saliva as well as TGF-β, IL-4 and IL-10 in plasma of gingivitis patients, relative to healthy controls, suggesting enhanced local humoral immunity." (PMID 34234776, 2021). "We explored levels of Th17/Treg-related cytokines, targeting TGF-β, IL-4, IL-6, IL-10 and IL-17, using ELISA, and found that all cytokines were significantly elevated in the gingivitis patients, relative to healthy controls." (PMID 34234776, 2021). "The objective of this study is to evaluate the salivary concentrations of IL-1β, IL-6, IL-8, IL-10, TNFα and IL-12p70 of DS individuals and compare to cerebral palsy (CP) and normoactive patients (all with gingivitis)." (PMID 32509226, 2020). "Finally, gingivitis produced changes in saliva, with salivary levels of GM-CSF, IL-6, IL-7, IL-15, IP-10, KC-like, IL-10, IL-18, MCP1, TNFα being statistically significantly higher in the saliva of CG2 dogs compared to CG1." (PMID 38521919, 2024). "Gingivitis is characterized by an inflammatory response; inflammatory molecules such as IL-6 and anti-inflammatory molecules such as IL-10 may be altered in saliva." (PMID 36547041, 2022). "The levels of 1β, IL-6, IL-8, and IL-10 were significantly higher in those with gingivitis." (PMID 36163488, 2022). "The concentrations of IL-1β, IL-6, IL-8 and IL-10 were elevated in the presence of gingivitis." (PMID 36163488, 2022). "However, TGF-β mRNA as well as TGF-β, IL-4, IL-6, IL-10 in the periperial blood and SIgA in the saliva were higher in the gingivitis group." (PMID 34234776, 2021). "The hypothesis of the study was that individuals with DS present higher levels of IL-1β, IL-6, IL-8, IL-10, TNFα and the p70 subunit of interleukin-12 (IL-12p70) cytokines when compared to individuals with CP and normoactive, all with gingivitis." (PMID 32509226, 2020). "Downregulated linoleic acid in plasma is observed in gingivitis patients and is connected to IL-17, TGF-β and IL-10 signalings, which are related closely to Th17 and Treg pathways." (PMID 37492568, 2023). "While other analytes were not significant amongst the sub-groups, there was a trend of lower α-amylase, higher IL-10, IgA, and TNF-α in the DMN with gingivitis group as compared to DMN with healthy periodontium." (PMID 35788667, 2022). "ELISA results revealed higher levels of IL-17A, IL-10, IL-6 and TGF-β in plasma of gingivitis patients relative to normal controls." (PMID 34234776, 2021). "In subjects with gingivitis, compared with the Cg group, levels of inflammatory factors IFN-γ, IL-4, IL-5, IL-6, IL-10 and IL-13 were significantly lower in saliva in the Dg group (p<0.05)." (PMID 33417619, 2021).
gingivitis (continued). "Taken together, a possible mechanism of gingivitis is that an increase in TGF-β content, coupled with IL-10 upregulation, in peripheral blood lymphocytes activated Treg cells, while transcription factor Foxp3 participated in a synergistic effect, thereby producing CD4+CD25+Foxp3+Treg cells." (PMID 34234776, 2021). "Furthermore, the bone-protective effect of IL-10 and the increase in IL-10 in the remission phase in MS could explain why relatively low PD with otherwise elevated clinical parameters of the MPI and BOP index (which can be seen in patients with signs of gingivitis) were present in our study." (PMID 38541692, 2024).
malnutrition (27 papers, 2011 to 2025). Inadequate nutrition resulting from poor diet, malabsorption, or abnormal nutrient distribution. "Our results indicate that malnutrition increases VL susceptibility due to defective IFN-γ-mediated immunity attributable to increased IL-10 production." (PMID 39527629, 2024). "Here, we found that malnutrition increases VL susceptibility due to an elevation in IL-10 production, which limits IFNγ-mediated immunity, iNOS production, and hepatic granuloma formation." (PMID 39527629, 2024). "Moreover, we identified IL-10 as an inflammatory determinant for associated morbidity and that IL-6-572 G/C and IL-10-1082 A/G SNPs contribute to the severity of malnutrition–inflammation and depressive symptoms." (PMID 37763079, 2023). "We found that malnutrition increases the susceptibility to VL due to defective IFN-γ-mediated immunity and hepatic granuloma formation due to an aberrant IL-10 response." (PMID 39527629, 2024). "Specifically, our findings indicate that the enhanced IL-10 levels in malnutrition further contribute to VL by disrupting Th1 immunity and hepatic granuloma formation, thereby limiting parasite clearance." (PMID 39527629, 2024). "In this piece of work, low constitutive blood bioactivities of INF-γ were found in both forms of acute weanling malnutrition that had been reported, in the previous year, to elicit high bioactivities of IL-10 and TGF-β." (PMID 38068780, 2023). "low concentrations of INF-γ, IL-2 and IL-12 coupled either with high concentrations of IL-10 or, at least, with levels of this cytokine that were apparently unaffected despite catabolic malnutrition." (PMID 38068780, 2023). "Based on Gomez criteria for malnutrition severity, children with mild malnutrition had lower IL-10 compared to children with severe malnutrition." (PMID 38434639, 2023). "Using the CIBER method, we identified that the most relevant determinant of malnutrition–inflammation and depressive symptomatology was IL-10 with coefficients (R2) of 0.05 and 0.11, respectively." (PMID 37763079, 2023). "The C allele of IL-6-572 G/C presented a small effect (GC–GG, δ = 0.27) on the MIS score; in contrast, the GG genotype of IL-10-1082 A/G showed a small effect on malnutrition–inflammation severity (GG–AA, δ =0.37)." (PMID 37763079, 2023). "WAT contains large lipid droplets and releases adipokines (FFAs, TNF-α, IL-6, IL-10, resistin, leptin, and adiponectin) to maintain metabolic homeostasis and stores TG for future energy production during periods of malnutrition." (PMID 33947969, 2021). "This is consistent with a recent report showing that in a model of malnutrition, glutamine supplementation decreased the levels of IL-10." (PMID 32214337, 2020). "Conversely, THI patients with low levels of cytokines had lower risk of malnutrition during their stay in the ICU, IL-10 and TNFα (p < 0.001 to 0.01), IL-6 and IL-1β (p 0.23 to 0.900)." (PMID 31443251, 2019). "The rats that were rescued from malnutrition in early life showed reduced transcription of NF-κB and IL-6 and increased transcription of IL-10 (an anti-inflammatory cytokine)." (PMID 25892856, 2015). "Other cytokines were mostly found to be elevated in malnutrition: IL10 was elevated in four of five studies, so was IL-4 and soluble receptors to Tumour Necrosis Factor-α." (PMID 25153531, 2014). "The findings confirm a previous report that constitutive IL-10 production in vivo is sustained even in the advanced stages of diverse forms of pre-pubescent malnutrition." (PMID 21318019, 2011). "Perhaps of more fundamental significance, the influence of acute malnutrition on second-tier production of IL-10, at least of the adaptive type, appears dependent on the metabolic form of malnutrition pathology." (PMID 21318019, 2011). "Similarly, within the cytokine profiles, IL-6 and IL-10 levels were notably higher in the moderate/severe malnutrition group than in the other groups, as demonstrated by post hoc analysis." (PMID 38474705, 2024).
malnutrition (continued). "Our results indicate that malnutrition increases VL susceptibility due to defective activation and expansion of CD4+ IFNγ+ T cells, decreased iNOS expression, and reduced hepatic granuloma formation, which is attributable to increased IL-10 production." (PMID 39527629, 2024). "Thus, we demonstrate that increased IL-10 production driven by malnutrition disrupts protective immunity against Leishmania, thereby enhancing the susceptibility of VL." (PMID 39527629, 2024). "The assay revealed robust net systemic production of IL-10, constitutively, even in advanced stages of malnutrition and, importantly, permitted the conclusion that the high blood concentrations of this tolerogenic cytokine were not a consequence of a reduced rate of turnover (catabolism)." (PMID 38068780, 2023). "Nutritional intervention increases IL-10 significantly in children aged 12–60 months old with moderate and severe malnutrition receiving curd (milk product) compared to leaf protein concentrate (LPC) (from 30.9 ± 29.5 to 67.4 ± 96.2 pg/mL vs. 29.2 ± 25.8 to 31.5 ± 24.9 pg/mL)." (PMID 38434639, 2023). "On the other hand, elevated IL-10 levels have been reported in many inflammatory conditions, including malnutrition, and may indicate attempts to inhibit inflammation by downregulating the secretion of pro-inflammatory cytokines." (PMID 31450770, 2019). "In addition, circulating adiponectin levels are decreased as IFN-γ and IL-10 levels are elevated in individuals with malnutrition and obesity, indicating that malnutrition promotes alterations in inflammatory cytokine production." (PMID 26880909, 2016). "Firstly, depletion of muscle tissue by malnutrition or disease could have disrupted the beneficial role of IL-10 production capacity in muscle repair and maintenance." (PMID 25040424, 2014). "Thus, the normal ontogenetic rise in LPS-stimulated IL-10 production was attenuated as malnutrition progressed in both forms of wasting pathology." (PMID 21318019, 2011). "Therefore, loss of LPS-responsive elements appears sufficient to explain the inability to sustain a normal ontogenetic rise in innate-type challenge-evoked IL-10 production in the two forms of malnutrition pursued in this investigation." (PMID 21318019, 2011). "However, lymphoid involution out of proportion with weight loss is a consistent feature of acute pre-pubescent malnutrition, and this phenomenon extends to the compartment of cells known to both express TLR-4 and produce IL-10." (PMID 21318019, 2011). "Interestingly, malnutrition enhances the frequency of NK cells and monocytes producing IL-10." (PMID 39527629, 2024). "Therefore, the effect of moderate malnutrition on IL-10 production was determined." (PMID 32033605, 2020). "In view of the robustness of constitutive IL-10 production in diverse forms of weanling malnutrition, confirmed herein, a decline in this cytokine response to external stimuli may provide an early sign that the ability to regulate immune competence is beginning to fail." (PMID 21318019, 2011). "In our study, patients with higher malnutrition scores had higher levels of inflammatory markers, such as CRP, IL-6 (Interleukin-6), and IL-10 (Interleukin-10), reinforcing the link between nutritional status and cytokine dysregulation." (PMID 40686821, 2025). "Previous studies have demonstrated a strong association between circulating inflammatory markers, such as CRP, IL-6, IL-10, and TNF-α, and malnutrition." (PMID 38474705, 2024). "In a study enrolled with eighty children aged one to five years with moderate and severe malnutrition showed increased TNF-α and IL-10 serum levels." (PMID 25095704, 2014). "Therefore, the present investigation points directly to the tolerance hypothesis with its finding that constitutive production of IL-10 is sustained in acute forms of malnutrition while production of this anti-inflammatory cytokine generally declines in response to external challenges." (PMID 21318019, 2011).
malnutrition (continued). "We found that malnutrition disrupts the ability to control parasite replication in the spleen and liver due to defective IFN-γ-mediated immunity, reduced hepatic granuloma formation, and enhanced IL-10 production." (PMID 39527629, 2024). "During the same interval of years, additional studies confirmed high blood bioactivities of IL-10 and TGF-β in the advanced stages of acute weanling malnutrition and also provided evidence that the blood levels of these tolerogenic cytokines rose early in the progression of weight loss." (PMID 38068780, 2023). "Malnutrition promotes the phenotypic transformation of immune cells to pro-inflammatory phenotypes, secreting pro-inflammatory cytokines such as IL-1β, IL-6, IL-8, TNF-α, and IL-2, while anti-inflammatory cytokines such as IL-1 receptor antagonists, IL-4, IL-10, and IL-13 decrease." (PMID 35003070, 2021). "Finally, serum levels of some inflammatory mediators, such as interleukin-6 or interleukin-10, were not tested in our study, and how inflammatory cytokines in malnutrition patients with non-albicans candidemia played a role in the risk of mortality requires further investigation." (PMID 34579094, 2021).